EMP2 (epithelial membrane protein 2)
Description:
Functions as a key regulator of cell membrane composition by regulating protein surface expression. Also, plays a role in regulation of processes including cell migration, cell proliferation, cell contraction and cell adhesion. Regulates transepithelial migration of neutrophils into the alveolar lumen, potentially via mediation of cell surface expression of adhesion markers and lipid raft formation (By similarity). Negatively regulates caveolae formation by reducing CAV1 expression and CAV1 amount by increasing lysosomal degradation. Facilitates surface trafficking and formation of lipid rafts bearing GPI-anchor proteins (By similarity). Regulates surface expression of MHC1 and ICAM1 proteins increasing susceptibility to T-cell mediated cytotoxicity (By similarity). Regulates the plasma membrane expression of the integrin heterodimers ITGA6-ITGB1, ITGA5-ITGB3 and ITGA5-ITGB1 resulting in modulation of cell-matrix adhesion. Also regulates many processes through PTK2. Regulates blood vessel endothelial cell migration and angiogenesis by regulating VEGF protein expression through PTK2 activation. Regulates cell contraction through PTK2 activation. Regulates focal adhesion density, F-actin conformation and cell adhesion capacity through interaction with PTK2. Positively regulates cell proliferation. Plays a role during cell death and cell blebbing. Promotes angiogenesis and vasculogenesis through induction of VEGFA via a HIF1A-dependent pathway. Also plays a role in embryo implantation by regulating surface trafficking of integrin heterodimer ITGA5-ITGB3. Plays a role in placental angiogenesis and uterine natural killer cell regulation at the maternal-fetal placental interface, however not required in the maternal tissues for a viable pregnancy (By similarity). Involved in the early stages of embryogenic development and cardiogenesis, potentially via regulation of epithelial-mesenchymal transition timing (By similarity). May play a role in glomerular filtration (By similarity).
Synonyms: XMP
Tractability: Antibody: UniProt places it where antibodies can reach, with high confidence; its Gene Ontology location is reachable by antibodies, with high confidence; UniProt predicts a signal peptide or a membrane-spanning region.
Gene: Protein-coding gene on chromosome 16 (10,528,422 to 10,580,689, reverse strand). Ensembl gene ENSG00000213853.
Subcellular location: Golgi apparatus membrane; Cell membrane; Apical cell membrane; Membrane raft; Cytoplasm; Nucleus; Cytoplasm, perinuclear region
Subcellular location (Human Protein Atlas): Nucleoplasm; Cytosol
Gene Ontology:
Molecular function: integrin binding; kinase binding; protein binding
Biological process: actin filament organization; actin-mediated cell contraction; apoptotic process; bleb assembly; blood vessel endothelial cell migration; cell adhesion; cell-matrix adhesion; embryo implantation; positive regulation of cell population proliferation; positive regulation of cell-matrix adhesion; positive regulation of integrin-mediated signaling pathway; protein localization to cell surface; regulation of angiogenesis; regulation of endothelial cell migration; regulation of glomerular filtration; regulation of kinase activity; regulation of vasculogenesis; caveola assembly; early endosome to late endosome transport; embryonic process involved in female pregnancy; heart formation; membrane raft assembly; natural killer cell proliferation; neutrophil migration; plasma membrane raft assembly; and 5 more
Cellular component: Golgi apparatus; Golgi membrane; plasma membrane; apical part of cell; apical plasma membrane; caveola; cell surface; cytoplasm; cytoplasmic vesicle; membrane; nucleus; membrane raft; perinuclear region of cytoplasm
Genetic constraint (gnomAD): Loss-of-function variants: 21 observed, 15.39 expected, observed/expected ratio (o/e) 1.36, 90% interval 0.96 to 1.86. The upper end of that interval is the gene's LOEUF score, 1.86, which puts it in group 6 of 6, group 1 being the genes least tolerant of losing a copy. Missense variants: 253 observed, 224.58 expected, observed/expected ratio (o/e) 1.13, 90% interval 1.02 to 1.25. Synonymous variants: 97 observed, 86.82 expected, observed/expected ratio (o/e) 1.12, 90% interval 0.95 to 1.32.
Homologues: Orthologues: chimpanzee EMP2 (99% identical), macaque EMP2 (93% identical), pig EMP2 (83% identical), guinea pig EMP2 (78% identical), mouse Emp2 (78% identical), tropical clawed frog emp2 (66% identical), zebrafish emp2 (58% identical), rat Emp2 (57% identical). Paralogues in human: PMP22 (43% identical), EMP3 (38% identical), EMP1 (37% identical), LIM2 (23% identical), TMEM202 (20% identical), GSG1L (19% identical), GSG1L2 (19% identical), GSG1 (16% identical), CLDND2 (16% identical), NKG7 (16% identical).
Diseases named in the same sentence as EMP2 in open-access papers:
EMP2 is named in the same sentence as 68 diseases in open-access papers, as found by Europe PMC text mining. Sharing a sentence is not in itself a finding about the gene and the disease. The quoted sentences say what the papers report.
breast cancer (13 papers, 2010 to 2025). A primary or metastatic malignant neoplasm involving the breast. "EMP2 levels are significantly increased during the progression from non-malignant glandular to ductal carcinoma in situ, invasive ductal carcinoma, and lymph node metastasis, suggesting the potential role of EMP2 in the late stage of breast cancer in association with tumor invasion and metastasis." (PMID 31652725, 2019). "On the contrary, the pro-metastatic role of the epithelial membrane protein 2 (EMP2) in breast cancer is well recognized." (PMID 38937754, 2024). "In human breast cancer cells, the anti-EMP2 antibody significantly inhibits the EMP2-mediated signal transduction and tumor invasion, and promote cell apoptosis, reducing tumor loading in human xenograft and murine metastatic models." (PMID 36217151, 2022). "In breast cancer, ovarian cancer, endometrial cancer, and other tumors, EMP2 levels are usually high, and the higher the expression level of EMP2 in these tumors, the stronger the invasion and metastasis ability of the tumor." (PMID 36217151, 2022). "EMP2 is not only a marker of human breast cancer stem cells but also a predictor of adverse clinical results." (PMID 36217151, 2022). "Transcriptional profiling analyses detected the dysregulation of EMP2 mRNA expression in breast cancers." (PMID 31652725, 2019). "Recently, EMP2 protein seems to have been identified as a novel biomarker to effectively capture circulating tumor cells (CTCs) in blood samples from patients with breast cancer." (PMID 31652725, 2019). "The associations of the Panel 2 markers MAL2, EMP2, CCNE2 and HJURP with short OS may point to different biological characteristics of the enriched cells and warrant further studies in aggressive breast cancer subtypes." (PMID 36831613, 2023). "EMP2 might be a more efficient biomarker for capturing CTC in breast cancer blood samples and is worthy of further assessments in clinical trials." (PMID 36217151, 2022). "Although anti-EMP2 IgG1 can considerably reduce tumor load (50–80%) in many in vivo breast cancer models, similar to all targeted therapies, anti-EMP2 IgG1 might require combination therapy with other drugs." (PMID 36217151, 2022). "Existing evidence suggests that anti-EMP2 treatment might be effective for EMP2-dependent breast cancer." (PMID 36217151, 2022). "ALDH1L2 has been previously proven to have correlation with EMP2 in breast cancer cells." (PMID 35799115, 2022). "MiR-133b played tumor suppressing roles in several malignancies through regulating in gastric cancer, targeting Sox9 in breast cancer, negatively regulating EMP2 in glioma, targeting methyltransferase DOT1L in colorectal cancer, and targeting EGFR in esophageal squamous cell carcinoma." (PMID 33816233, 2021). "Moreover, treatment of breast cancer cells with anti-EMP2 IgG1 promotes cell death and inhibits cancer cell invasion." (PMID 31652725, 2019). "EMP2 mRNA expression might be negatively regulated by breast cancer-related receptors (estrogen receptor, progesterone receptor, and ErbB2), because the expression is relatively high in the triple-negative breast cancer cells." (PMID 31652725, 2019). "Previous efforts in developing EMP2-targeting therapies, such as the granzyme B fusion protein GrB-Fc-KS49, have demonstrated promising therapeutic potential for targeted breast cancer treatment." (PMID 41173824, 2025). "Worthy, the signature demonstrated to predict poor outcomes in breast cancer patients exhibiting high transcriptional levels of ITGA11, THBS1, FN1, EMP1, ITGA2, FYN, SPP1, and EMP2." (PMID 38937754, 2024). "In a recent study, using RT-qPCR, two panels of transcripts related to the presence of CTCs (Panel 1: CK19, EpCAM, SCGB2A2 and Panel 2: EMP2, SLC6A8, HJURP, MAL2, PPIC and CCNE2), in two cohorts of breast cancer patients (metastatic and early), were evaluated." (PMID 37046848, 2023).
breast cancer (continued). "In the breast cancer cell line MCF-7, EMP2 maps to a broad domain node and is connected to multiple super enhancers, which are also connected to each other." (PMID 29089515, 2017). "A panel of six genes: CCNE2, DKFZp762E1312, EMP2, MAL2, PPIC, and SLC6A8 that were over-expressed in the blood of 81% of patients with recurrent breast cancer was then chosen as gene markers for the molecular detection of CTC." (PMID 21129172, 2010). "In our present study, we evaluated two panels of transcripts related with the presence of circulating tumor cells (CTCs) (Panel 1: CK19, EpCAM, SCGB2A2 and Panel 2: EMP2, SLC6A8, HJURP, MAL2, PPIC and CCNE2) in two cohorts of breast cancer patients (metastatic and early)." (PMID 36831613, 2023). "The observation that anti-EMP2 IgG1 slowed tumor growth in breast cancer xenografts without detectable systemic toxicity indicates its immunotherapeutic value for the treatment of tumors with positive EMP2 expression." (PMID 33799364, 2021). "We have shown that the RT-qPCR-based multi-marker analysis using the six genes: CCNE2, DKFZp762E1312, EMP2, MAL2, PPIC, or SLC6A8 more than doubled the number of positive patients with recurrent breast cancer compared to the analysis of hMAM or EpCAM gene expression alone." (PMID 21129172, 2010). "Indeed, EMP2 and PPIC transcripts in spiked blood samples indicated the presence of Hs579T breast cancer cells; in contrast, the analysis of the epithelial markers EpCAM, CK19 and SCGB2A2 alone would not have detected these hormone receptor and HER2-negative cells." (PMID 36831613, 2023).
endometrial cancer (10 papers, 2008 to 2025). Primary or metastatic malignant neoplasm involving the endometrium (mucous membrane that lines the endometrial cavity). "EMP2 is a protein implicated in progression and survival in endometrial cancer, and recently it was proposed as a possible oncoprotein." (PMID 33265245, 2018). "These prior studies demonstrated the therapeutic potential of EMP2-targeting strategies in breast, ovarian, and endometrial cancers." (PMID 41173824, 2025). "EMP2 has been reported as an oncogene in invasive breast cancer and endometrial carcinoma, and is expected to be a novel target for cancer treatment." (PMID 41173824, 2025). "Other studies have shown that EMP2 is co-expressed with tumor stem cell-related marker aldehyde dehydrogenase 1 (ALDH1) in endometrial cancer." (PMID 36217151, 2022). "The expression of EMP2 in endometrial cancer patients' tissues positively correlates with endometrial cancer malignancy." (PMID 36217151, 2022). "Using EMP2 to identify endometrial cancer and CTCs demonstrated its potential as a tumor molecular diagnostic marker." (PMID 36217151, 2022). "Endometrial cancer with high EMP2 expression has stronger myometrial invasiveness, higher clinical stage, stronger recurrence probability, and mortality, and it is more challenging to treat." (PMID 36217151, 2022). "For example, EMP1 promotes tumor metastasis by enhancing cell migration in prostate cancer, whereas EMP2 acts as an oncogenic protein in endometrial cancer cells, with high EMP2 related to increased lymphovascular invasion and poor survival." (PMID 33799364, 2021). "Treatment of ovarian and endometrial cancer cells with the anti-EMP2 diabodies inhibits cell growth and increases apoptosis." (PMID 31652725, 2019). "The anti-EMP2 recombinant bivalent antibody fragments (diabodies) reduce the aggressiveness of endometrial cancer cells." (PMID 31652725, 2019). "The protein level of EMP2 positively correlates with the progression of endometrial cancer, gradually increasing in the order benign, hyperplasia, atypical hyperplasia, and endometrial adenocarcinoma." (PMID 31652725, 2019). "EMP2 mediates angiogenesis in endometrial cancer by regulating the expression of VEGF and hypoxia-induced transcription factors-1α through Src." (PMID 31652725, 2019). "Conversely, EMP2 was identified as an early predictor of endometrial cancers with unfavorable outcome by activation of protein tyrosine kinase 2 (PTK2 or FAK) and v-src avian sarcoma viral oncogene homolog (SRC)." (PMID 25940704, 2015). "The residualizing agent, 64Cu-DOTA anti-EMP2 minibody, achieved high uptake in endometrial cancer xenografts overexpressing EMP2 (10.2 ± 2.6, percent injected dose per gram (%ID/g) ± SD) with moderate uptake in wild-type HEC1A tumors (6.0 ± 0.1)." (PMID 22585360, 2013). "In this report, we investigate the regulation of EMP2 using a combination of archived human tissue, the human endometrial cancer cell line RL95-2 in vitro, and hormonally manipulated native mouse endometrium in vivo." (PMID 18400107, 2008). "Moreover, detailed analysis of EMP2 in potential precancerous lesions suggests that EMP2 positivity strongly predicts the progression of endometrial cancer." (PMID 39866225, 2025). "Notably, tissue microarray (TMA) demonstrated a significant incremental rise in EMP2 expression levels from benign to malignant endometrial cancer." (PMID 41173824, 2025). "The response of EMP2 to progesterone and estradiol was determined using a combination of real-time PCR, SDS-PAGE/Western blot analysis, and confocal immunofluorescence in the human endometrial carcinoma cell line RL95-2." (PMID 18400107, 2008).
glioblastoma (7 papers, 2018 to 2025). The most malignant astrocytic tumor (WHO grade IV). "In this study, we attempt to build upon our laboratory work with an investigation of EMP2 in clinical glioblastoma samples, and we specifically examine the effects of EMP2 following antiangiogenic treatment." (PMID 33063013, 2020). "Given the widespread usage of antiangiogenics in glioblastoma treatment, we examined the effects of bevacizumab on EMP2 levels." (PMID 33063013, 2020). "The IVY Glioblastoma Atlas Project database was used to evaluate EMP2 expression levels in 270 samples by differing histological areas of the tumor." (PMID 33063013, 2020). "EMP2 is a cell surface protein found in glioblastoma that serves to increase angiogenesis in cell line models." (PMID 33063013, 2020). "Epithelial membrane protein 2 (EMP2) is a cell surface protein that has been previously shown to be expressed in glioblastoma, correlate with poor survival, and regulate neoangiogenesis in cell lines." (PMID 33063013, 2020). "These clinical data supplement our existing data suggesting EMP2 as a potential therapeutic target in glioblastoma." (PMID 33063013, 2020). "Despite these limitations, we believe this clinical data translate previous work in cell lines to highlight the potential of EMP2 as a biomarker for antiangiogenic therapy in glioblastoma." (PMID 33063013, 2020). "In this study, we evaluate the relationship between EMP2 and bevacizumab in a series of clinical glioblastoma specimens, and we identify increased EMP2 expression in tumor samples after bevacizumab treatment, proportional to the length of bevacizumab treatment." (PMID 33063013, 2020). "As anti EMP2 antibody could affect the tumor inhibition of glioblastoma, further evaluation and validation of EMPs expression in high grade mesenchymal tumors are required." (PMID 32857809, 2020). "After bevacizumab therapy, EMP2 protein expression levels increase in a manner proportional to the length of therapy, and specifically, protein expression was enriched in areas of angiogenesis in glioblastoma." (PMID 33063013, 2020). "Overall, we hypothesize that these data suggest further study on EMP2 in the treatment response and resistance to bevacizumab as well as further evaluation as a tool to assess antiangiogenic therapies in glioblastoma." (PMID 33063013, 2020). "However, EMP2 has been reported to be highly expressed in glioblastoma and in human samples and a mouse model; further, the anti-EMP antibody showed efficacy in tumor inhibition." (PMID 32857809, 2020). "We hypothesize a role of EMP2 in clinical bevacizumab resistance and as a potential antiangiogenic therapeutic target in glioblastoma." (PMID 33063013, 2020). "Furthermore, differences in progression-free and overall survival in patients correlated with altered levels of EMP2 from tumor tissue after resection of newly diagnosed glioblastoma." (PMID 33063013, 2020). "EMP2 H-scores from 16 tumor samples obtained from patients undergoing initial resection for newly diagnosed glioblastoma were compared to EMP H-scores obtained from 17 patients undergoing subsequent resection after bevacizumab treatment for recurrent glioblastoma." (PMID 33063013, 2020). "Mechanistically, EMP2’s regulatory role in activating FAK and Src kinases drives endometrial tumor formation and enhances glioblastoma (GBM) growth." (PMID 41173824, 2025). "Besides EMP1, EMP2 has been shown to be upregulated in more than 70% of both serous and endometrioid ovarian cancers, and to enhance tumor growth of glioblastoma by promoting angiogenesis, partially by increasing vascular endothelial growth factor-A expression in glioblastoma cells." (PMID 29867202, 2018). "Indeed, methylation of EMP1 and EMP2 in human cancer is rarely reported, although methylation of EMP3 was previously detected in NSCLC and glioblastoma, suggesting different gene regulatory programs in EMPs." (PMID 33799364, 2021).